NMT2 (N-myristoyltransferase 2)
Diseases named in the same sentence as NMT2 in open-access papers:
NMT2 is named in the same sentence as 27 diseases in open-access papers, as found by Europe PMC text mining. Sharing a sentence is not in itself a finding about the gene and the disease. The quoted sentences say what the papers report.
breast carcinoma (3 papers, 2018 to 2024). "Because loss of NMT2 protein in breast cancer favored better patient prognosis, we investigated whether breast cancer cells were susceptible to NMT inhibition using the pan-NMT inhibitor PCLX-001 both in vitro, and in an in vivo animal model." (PMID 33398478, 2021). "To determine if differences in NMT2 protein levels correlated with disease prognosis in these breast cancer patients, we performed Kaplan–Meier overall survival (OS) analysis using the clinical outcomes associated with each breast adenocarcinoma sample." (PMID 33398478, 2021). "While NMT2 protein was readily detected in normal breast epithelial tissue, it was undetectable in the majority of breast cancers." (PMID 33398478, 2021). "Our investigation of NMT2 transcript-binding miRNAs revealed miR-411-5p and miR-187, which respectively function as a tumor suppressor and an oncogenic agent of breast cancer." (PMID 29579063, 2018). "We also identified NMT2-targeting miRNAs that have been previously demonstrated to play a role in regulating or advancing colorectal and breast cancers." (PMID 29579063, 2018). "This suggests that while NMT2 may relate to breast cancer outcomes, it does so in parallel with other known prognostic factors." (PMID 33398478, 2021). "As NMT2 expression can be lost during carcinogenesis and carries prognostic value, there may be additional biology, yet to be revealed, that can be exploited to further improve breast cancer patient outcomes." (PMID 33398478, 2021). "We found that NMT1 protein levels correlated with poor prognosis in general and that NMT2 protein could not be detected in the majority of breast cancer samples and when it was detected it was linked with a poorer prognosis." (PMID 33398478, 2021). "In patient samples, single CpG methylation at position 15,212,066 (cg02268561 beta values) showed significant inverse correlation with NMT2 expression in DLBCL, acute myeloid leukemia (AML), and breast cancers (p < 0.05) and occurred in two of the five DLBCL tumors tested." (PMID 38715059, 2024). "To begin our assessment of NMT2 expression in breast carcinoma, we compared the relative expression of NMT2 proteins in normal and cancerous tissue samples using IHC." (PMID 33398478, 2021). "While a very high proportion of breast cancer samples had detectable NMT1 protein levels (602 of 666 tumors), a large proportion (509 of 706 tumors) exhibited very low or undetectable amounts of NMT2 despite normal breast epithelia being ubiquitously positive for NMT2 proteins." (PMID 33398478, 2021).
heart failure (2 papers, 2025). Inability of the heart to pump blood at an adequate rate to meet tissue metabolic requirements. "Although NMT1 and NMT2 share ~77% sequence identity, NMT2 in particular plays a significant role in cardiac remodeling and heart failure, with affected patients exhibiting up to a 60% decrease in cardiomyocyte NMT2 levels compared to healthy individuals." (PMID 40859030, 2025). "In addition, drugs targeting NMTs (NMT1 and NMT2) have been suggested to be potent senolytics and a target for treating or preventing various diseases such as cancer and heart failure." (PMID 40792619, 2025). "Dysregulation of NMT2, but not NMT1, has been linked to heart failure and cardiac hypertrophy." (PMID 40859030, 2025).
lymphoma (2 papers, 2020 to 2024). A malignant (clonal) proliferation of B- lymphocytes or T- lymphocytes which involves the lymph nodes, bone marrow and/or extranodal sites. "Since lymphoma cells and tumors showed the highest prevalence of NMT2 loss, we investigated the mechanisms involved in this cancer type." (PMID 38715059, 2024). "Thus, NMT2 loss is common in lymphomas and associated with more aggressive DLBCL." (PMID 38715059, 2024). "The data also illustrate that while the expression of NMT2 is higher in cancer cell lines of CNS, kidney and fibroblast origins there is a selective and significant reduction of NMT2 expression in hematological cancers such as leukemia, lymphoma and myeloma." (PMID 33093447, 2020). "Each inhibitor resulted in time- and concentration-dependent recovery of NMT2 mRNA levels in lymphoma cell lines, but not in the normal immortalized B cell line IM9." (PMID 38715059, 2024). "Interestingly, the low NMT2 expression levels seen in lymphomas, leukemia and other cell lines were not compensated by an increase in NMT1 expression." (PMID 33093447, 2020). "Bisulfite sequencing of chromosomal DNA from lymphoma cell lines and immortalized IM9 B cells confirmed that these NMT2 loci were methylated (dark spheres) in DOHH2 and WSU-DLCL2 lymphoma cells, but not in BL2, benign IM9 cells, and lymphocytes (open circles)." (PMID 38715059, 2024).
ovarian carcinoma (2 papers, 2021 to 2024). A malignant neoplasm originating from the surface ovarian epithelium. "Further analysis of TCGA database showed that the loss of NMT2 is also associated with poorer patient survival in acute myeloid leukemia (AML), glioma, kidney, and ovarian cancers, validating the importance of NMT2 in oncogenesis and patient outcome." (PMID 38715059, 2024). "However, suppression of both NMT1 and NMT2 can induce apoptotic effect on ovarian cancer cell line, SK-OV-3, with NMT2 inhibition showing greater apoptotic effect compared with NMT1." (PMID 34095144, 2021). "Indeed, compared to normal tissues, NMT2 expression was significantly decreased in multiple tumor types (9/11) and metastatic tissues, including breast, lung, colon, and ovarian cancers, whereas NMT1 expression was significantly increased in multiple tumor types (8/11), and metastases." (PMID 38715059, 2024).
breast adenocarcinoma (1 paper, 2021). "These mAbs were used to perform immunohistochemical analysis of the abundance and distribution of NMT1 and NMT2 in normal breast epithelial samples and a large cohort of primary breast adenocarcinomas from the BCIRG001 clinical trial (n = 706)." (PMID 33398478, 2021). "By comparison, 509 of 706 primary breast adenocarcinoma tumor samples obtain from participants in the BCIRG 001 clinical trial were found to be NMT2 negative." (PMID 33398478, 2021).
colorectal cancer (1 paper, 2014). A primary or metastatic malignant neoplasm that affects the colon or rectum. "There is some evidence that NMT2 may play a role in the pathogenesis of human colorectal cancer." (PMID 24619124, 2014).
ductal carcinoma in situ (1 paper, 2012). "Another pair of oncogenic gene regulators, miR-182 and miR-183, are overexpressed in ductal carcinoma in situ (DCIS) and lead to increased expression of chromobox homolog 7 (CBX7), DOK4, NMT2, and EGR1." (PMID 23202960, 2012).
kidney failure (1 paper, 2019). An acute or chronic condition that is characterized by the inability of the kidneys to adequately filter the blood. "The SNV rs10906850 nearby NMT2 was significantly associated with ICD code for renal/kidney failure (p = 0.008) and rs11645800 nearby CDH8 was nominally associated with renal/kidney failure." (PMID 31178898, 2019).
liver cancer (1 paper, 2021). An epithelial or non-epithelial malignant neoplasm that arises from the liver. "Here, N-myristolyation and its enzyme NMT1, but not NMT2, were found to be critical in liver cancer." (PMID 34136404, 2021). "Via tissue microarray assay (TMA), we further confirmed that NMT1 but not NMT2, another NMT member, was elevated in liver cancer." (PMID 34136404, 2021).
lung carcinoma (1 paper, 2023). "Although both NMT1 and NMT2 are expressed in lung cancer cells, AMPK is only specifically regulated by NMT1." (PMID 37140999, 2023).
lupus (1 paper, 2018). "The B-cells of lupus patients were determined to have increased expression of miR-148, an NMT1-transcript-binding miRNA, and decreased expression of miR-1246, an NMT2-transcript-binding miRNA." (PMID 29579063, 2018).
squamous cell carcinoma (1 paper, 2025). A carcinoma arising from squamous epithelial cells. "Real-time quantitative PCR (qPCR) revealed that NMT1 mRNA levels were significantly elevated under hypoxia in three hypoxia-responsive squamous cell carcinoma cell lines (SCC9, SIHa, and KYSE-510), whereas NMT2 levels remained unchanged." (PMID 40605065, 2025).
cancer (10 papers, 2017 to 2025). A tumor composed of atypical neoplastic, often pleomorphic cells that invade other tissues. "Overall, although our data showed that NMT2 loss is an important component of PCLX-001 sensitivity, cancer cell dependence on NMT1 for survival was even more important, particularly in NMT2-deficient cancer cells." (PMID 38715059, 2024). "Overall, while NMT2 loss initially appeared to be a significant component of NMTI sensitivity, cancer cell dependency on NMT1 for survival is even more important, particularly in NMT2-deficient cancer cells." (PMID 38715059, 2024). "Our results confirm the requirement of NMT1 for cell survival, and genetically validated the pharmacological targeting of NMTs with an NMTI for cancer therapy, especially in cancers with a highly prevalent loss of NMT2." (PMID 38715059, 2024). "Prompted by the highly prevalent loss of NMT2 expression in various cancers, especially in hematologic cancers, we sought to target the remaining NMT1 with the potent pan-NMT inhibitor PCLX-001 in a manner reminiscent of synthetic lethality, thereby sparing normal cells with two NMTs." (PMID 38715059, 2024). "The researchers proposed that the greater susceptibility of haematological cancer cells than other cancer cells to PCLX-001 may result from altered expression of NMT1 or NMT2." (PMID 37140999, 2023). "NMT2 expression was significantly lower in hematologic cancers (cell lines and tumors) in comparison to cancers of other origins." (PMID 38715059, 2024). "We investigated the expression of NMTs in numerous cancers and found that NMT2 levels are dysregulated by epigenetic suppression, particularly so in hematologic malignancies." (PMID 38715059, 2024). "Analysis of CCLE NMT1 or NMT2 expression data reveals that in addition to be overexpressed in some cancers (aka the current dogma), NMT expression levels are actually lower in other cancers, many of which are of hematological origin." (PMID 33093447, 2020). "The association of microRNAs (miRNAs) that target N-myristoyltransferase (NMT) transcript 1 and 2 (NMT1 and NMT2) with different cancer types and their expression changes." (PMID 29579063, 2018). "NMT2 catalyzes N-myristoylation of multiple proteins and its depletion in cancer cells results in dramatic increase of apoptosis." (PMID 29272308, 2017). "Interestingly, cancer cells that were low in NMT2, highly dependent on NMT1, or predicted to be sensitive to NMTI treatment (high MISS-54 score) showed high MYC expression." (PMID 38715059, 2024). "Therefore, cancer cells low in NMT2 are likely to be low in NMT1 and possibly easier to eliminate pharmacologically because they have fewer enzymatic targets than normal cells." (PMID 38715059, 2024). "Interestingly, NMT1 dependency was significantly correlated with NMT2 expression in all cancer cell lines (r = 0.600; p < 0.0001)." (PMID 38715059, 2024). "Expression of NMT1 is relatively constant across the 1269 cell lines investigated with a slight but significant decrease in expression in breast and leukemia cancer cell lines while NMT2 expression varies significantly amongst various cancers and also within a given cancer type." (PMID 33093447, 2020). "Because NMT2 loss, which we now demonstrate to occur via epigenetic suppression, could not explain by itself the sensitivity of all types of cancer cells to PCLX-001, we hypothesized that other genes were involved." (PMID 38715059, 2024). "The accurate identification of NMT1 and NMT2 protein levels may be of particular importance in cancer since numerous cancer types were previously demonstrated to exhibit variabilities in NMT expression/protein levels and because of this may be targeted with NMT-directed therapeutics." (PMID 33398478, 2021). "First, the development of NMT inhibitors as anti-cancer therapeutics, which is the aim of this work, restricts the targets to human NMT1 and NMT2." (PMID 36080246, 2022).
cancer (continued). "Although we still do not know why hematological cancer cells are more vulnerable to PCLX-001 than other cancer cell types, we think this is possibly related to altered expression of either NMT1 or NMT2." (PMID 33093447, 2020). "While we still do not know why hematological cancer cells are more vulnerable to PCLX-001 than other cancer cell types, we think this might be related to alterations in NMT1 or NMT2 expression in hematological cancer cells." (PMID 33093447, 2020). "Since NMT2 expression alone could not explain the spectrum of cancer cell vulnerability to NMTIs, we developed a 54 gene set named MISS-54 reflecting the expression profile of cells sensitive to PCLX-001 or PCLX-002 in comparison to resistant cells." (PMID 38715059, 2024). "CRISPR/Cas9 KOs in 1078 cancer cell lines revealed that while NMT2 (average gene effect score = 0.171 ± 0.003) is a non-essential gene, NMT1 can be characterized as an essential gene in cancer cells with an average gene effect score of 0.855 ± 0.015." (PMID 38715059, 2024). "Whereas we cannot completely rule out a role for NMT2 in lysosomal metabolism, we observed that silencing of NMT1 was sufficient to recapitulate the effects of NMTi treatment, indicating that NMT1 is likely the main enzyme involved in regulating lysosomal functions in cancer cells." (PMID 32686708, 2020).
tumor (7 papers, 2017 to 2024). "Due to the loss of NMT2 expression in certain tumor types, there is a growing interest in developing selective inhibitors for NMT1." (PMID 37511367, 2023). "Consequently, the loss of NMT2 could help drive tumor development." (PMID 38715059, 2024). "In fact, intramural injection of NMT-specific siRNA, both NMT1 and NMT2 specific siRNAs reduced tumor growth." (PMID 28713376, 2017). "Normal breast epithelial elements adjacent to tumor on the TMA were universally positive for NMT2 (1–2+) on a 0–3 scale, scored as 0 absent; 1+ weak staining; 2+ moderate staining; 3+ strong staining." (PMID 33398478, 2021). "However, injection of NMT2-specific siRNA alone failed to reduce tumor growth." (PMID 28713376, 2017).
hematological cancer (3 papers, 2020 to 2024). "Third, it has been reported that the expression of the NMT2 gene is significantly decreased or even completely lost in certain hematological cancer types; hence, the development of a selective NMT1 inhibitor is of interest to the biotech industry." (PMID 36080246, 2022). "Altogether, we find a reduction in NMT2 expression in hematological cancer cell lines, which may account for their increased sensitivity to PCLX-001." (PMID 33093447, 2020). "Databases analyses revealed that NMT2 expression levels varied significantly more than those of NMT1, and that hematologic cancer cell lines comprised the vast majority of the lowest NMT2 expressing cells." (PMID 38715059, 2024). "After describing the absence of NMT2 in most hematologic cancer cell lines and tumors, and their high sensitivity towards PCLX-001, we hypothesized that NMTI could exploit this loss by targeting the remaining NMT1 in an approach reminiscent of synthetic lethality." (PMID 38715059, 2024).
infection (3 papers, 2018 to 2024). The state of being infected such as from the introduction of a foreign agent such as serum, vaccine, antigenic substance or organism. "In the matching WB, the expression of NMT1 or NMT2 seemed constant across time and unaffected by infection." (PMID 39625987, 2024). "HAP1 NMT1ko were transfected with control plasmids (empty vector or expressing HA-mCherry) or plasmids expressing N-terminal HA tagged NMT1 or NMT2 before infection with MOPV (MOI 0.01)." (PMID 39625987, 2024). "We characterized the interaction of the Z matrix protein with NMT1 and NMT2 and found that during infection NMT1 has a predominant role for all Mammarenavirus tested." (PMID 39625987, 2024). "We measured mRNA levels of both enzymes in A549 cells and found that there was three to four times more mRNA encoding for NMT1 than NMT2 in cells regardless to the presence or the absence of infection, a result similar to observations in other cell lines." (PMID 39625987, 2024). "We then tested in identical condition of infection whether NMT1 and/or NMT2 were able to interact with the Z matrix protein during infection." (PMID 39625987, 2024). "We first showed that during infection the Z matrix protein interacted with NMT1 and NMT2, the enzymatic nature of this interaction rendering it likely difficult to grasp and detect." (PMID 39625987, 2024). "Lastly, miR-132 (NMT1-transcript-binding miRNA) and miR-29 (NMT2-transcript-binding miRNA) are involved in HIV infection, with the former promoting infection and the latter acting as an antiviral agent." (PMID 29579063, 2018). "Furthermore, miRNAs of interest may be overexpressed (gain-in-function) in cell lines through a lentiviral infection or plasmid transfection to determine their effect on NMT1/NMT2/METAP2 mRNA transcript levels using qPCR and the resulting protein expression by Western blot analysis." (PMID 29579063, 2018). "Both enzymes are present at the protein levels in our cellular extracts but we could not clearly differentiate the location of NMT1 and NMT2, nor evidence the location of their interaction with the Z matrix protein during infection." (PMID 39625987, 2024).
infectious disease (1 paper, 2018). A disorder directly resulting from the presence and activity of a microbial, viral, or parasitic agent in humans. "The association of microRNAs (miRNAs) that target N-myristoyltransferase (NMT) transcript 1 and 2 (NMT1 and NMT2) and MetAP transcripts with different infectious diseases and their expression changes." (PMID 29579063, 2018).
NMT2 also shares sentences with these, for which no sentence is quoted: acute myeloid leukemia (1 paper); breast tumors (1); cardiac hypertrophy (1); colon cancers (1); glioma (1); hematologic malignancies (1); leukemia (1); myeloma (1); Sepsis (1); type 2 diabetes (1).